CLEC10A (C-type lectin domain containing 10A)
Description:
C-type lectin receptor involved in recognition of N-acetylgalactosamine (GalNAc)-terminated glycans by myeloid antigen presenting cells (APCs). Binds in a Ca(2+)-dependent manner to alpha- and beta-linked GalNAc residues on glycoprotein and glycolipid antigens, including alphaGalNAc- and Galbeta1->3GalNAc-O-Ser/Thr also known as Tn and T antigens, LacdiNAc epitope GalNAcbeta1->4GlcNAc and its derivative GalNAcbeta1->4-(Fucalpha1->3)GlcNAc, O-linked core 5 and 6 glycans, and GM2 and GD2 gangliosides. Acts as a signaling receptor at the interface of APC-T cell interactions. On immature dendritic cells, recognizes Tn antigen-carrying PTPRC/CD45 receptor on effector T cells and downregulates PTRPN/CD45 phosphatase activity with an impact on T cell activation threshold, cytokine production and proliferation. Modulates dendritic cell maturation toward a tolerogenic phenotype leading to generation of regulatory CD4-positive T cell subset with immune suppressive functions. Acts as an endocytic pattern recognition receptor involved in antitumor immunity. During tumorigenesis, recognizes Tn antigens and its sialylated forms Neu5Ac-Tn and Neu5Gc-Tn expressed on tumor cell mucins. On immature dendritic cells, can internalize Tn-terminated immunogens and target them to endolysosomal compartment for MHC class I and II antigen presentation to CD8-positive and CD4-positive T cells, respectively.
Synonyms: DC-ASGPR; MGL; CD301; CLECSF13; CLECSF14; HML; HML2
Tractability: Small molecule: a structure with a bound ligand is known. Antibody: UniProt places it where antibodies can reach, with high confidence; its Gene Ontology location is reachable by antibodies, with high confidence; UniProt predicts a signal peptide or a membrane-spanning region. PROTAC: its protein half-life has been measured.
Gene: Protein-coding gene on chromosome 17 (7,074,537 to 7,081,166, reverse strand). Ensembl gene ENSG00000132514.
Subcellular location: Cell membrane; Early endosome membrane; Lysosome membrane
Pathways (Reactome):
Immune System: Dectin-2 family
Gene Ontology:
Molecular function: protein binding; carbohydrate binding; D-mannose binding; fucose binding; pattern recognition receptor activity
Biological process: immune response
Cellular component: early endosome membrane; lysosomal membrane; plasma membrane; external side of plasma membrane
Genetic constraint (gnomAD): Loss-of-function variants: 37 observed, 39.82 expected, observed/expected ratio (o/e) 0.93, 90% interval 0.71 to 1.22. The upper end of that interval is the gene's LOEUF score, 1.22, which puts it in group 5 of 6, group 1 being the genes least tolerant of losing a copy. Missense variants: 283 observed, 331.94 expected, observed/expected ratio (o/e) 0.85, 90% interval 0.77 to 0.94. Synonymous variants: 122 observed, 133.05 expected, observed/expected ratio (o/e) 0.92, 90% interval 0.79 to 1.07.
Homologues: Orthologues: chimpanzee CLEC10A (98% identical), macaque CLEC10A (86% identical), dog CLEC10A (67% identical), mouse Mgl2 (57% identical), pig CLEC10A (52% identical), rat Clec10a (50% identical), mouse Clec10a (47% identical), Drosophila melanogaster tfc (20% identical), Caenorhabditis elegans clec-266 (18% identical), Caenorhabditis elegans clec-88 (16% identical), Caenorhabditis elegans clec-87 (15% identical), Drosophila melanogaster CG14866 (15% identical), and 5 more. Paralogues in human: ASGR1 (58% identical), ASGR2 (49% identical), CLEC17A (25% identical), CD209 (23% identical), CLEC4E (23% identical), CLEC4A (22% identical), CLEC4M (22% identical), CLEC6A (20% identical), CLEC4C (20% identical), FCER2 (20% identical), CLEC4F (20% identical), CLEC4G (19% identical), and 2 more.
Diseases named in the same sentence as CLEC10A in open-access papers:
CLEC10A is named in the same sentence as 101 diseases in open-access papers, as found by Europe PMC text mining. Sharing a sentence is not in itself a finding about the gene and the disease. The quoted sentences say what the papers report.
breast carcinoma (29 papers, 2011 to 2026). "Hormone depletion by TAM induced CLEC10A ligands on damaged cells, and, in breast cancer patients, positivity of CLEC10A in tumor tissue is associated with improved disease-free and overall survival." (PMID 36009853, 2022). "In breast cancer patients, positivity for CLEC10A staining in tumor tissues was associated with improved outcome and survival." (PMID 31455323, 2019). "Single-cell RNA sequencing of human breast cancers revealed that CLEC10A is expressed in cDC2 and select macrophage subsets." (PMID 42147159, 2026). "Approximately 30% more cells of the macrophage subtypes positive for LAM2_APOE, LAM1_FABP5 and EGR1, respectively, expressed CLEC10A in TNBC in comparison with ER+ / HER2+ breast cancer (Chi-squared p < 0.001)." (PMID 38206856, 2024). "Given that positive staining for CLEC10A can be induced by hormone depletion or cell damaging agents, we investigated the clinical impact of CLEC10A positivity on breast cancer progression and survival." (PMID 31455323, 2019). "The biological and immunological functions of CLEC10A and CLEC10A ligands in breast cancer are pertinent questions to be resolved in future studies." (PMID 31455323, 2019). "For the identification of glycoproteins bound by CLEC10A, pull down experiments with immobilized CLEC10A were performed on whole cellular extracts of two breast cancer samples positively stained by CLEC10A." (PMID 31455323, 2019). "Multivariate Cox regression analysis demonstrated that positivity for CLEC10A is an independent prognostic marker for overall survival (hazard ratio: 0,45 (95% ci: 0,23 - 0,90) in addition to advanced stages of breast cancer disease." (PMID 31455323, 2019). "Moderate and strong positivity of CLEC10A staining was observed in 36% (n = 53) of breast cancer specimens while 64% (n = 93) of tumors were weakly positive or stained negative." (PMID 31455323, 2019). "Based on protein domain histochemistry, we previously investigated the binding of the glycoreceptor CLEC10A to breast cancer tissue." (PMID 31455323, 2019). "Single-cell RNA sequencing of human breast cancers showed that the human ortholog CLEC10A is expressed in cDC2-like dendritic cells and select macrophage subsets, suggesting a conserved role for CD301+ myeloid populations." (PMID 41377951, 2025). "Intriguingly, among these downregulated genes, CLEC10A and PTPRT have been demonstrated as poor prognostic factors when their expressions were reduced in breast cancer, suggesting a plausible negative regulatory mechanism of these miRNAs in our TRM signature." (PMID 35805995, 2022).
melanoma (25 papers, 2008 to 2025). A malignant, usually aggressive tumor composed of atypical, neoplastic melanocytes. "Our results demonstrate that high CLEC10A expression was associated with improved melanoma survival and immune scores, indicating its potential role in anti-tumoral immunity." (PMID 33868993, 2021). "Preliminary results showed that treatment of melanoma-bearing mice with svL4 caused a dramatic reduction in TREG cells within tumors (data not shown), which possibly resulted from nudging M2a cells to the more phagocytic M2b macrophages by engaging CLEC10A." (PMID 29665849, 2018). "The four genes (CLEC7A, CLEC10A, HAPLN3, and HCP5) were also identified as meaningful anti-tumoral genes in melanoma." (PMID 33868993, 2021). "Three genes, i.e., CLEC7A, CLEC10A, and HAPLN3 have been reported to exhibit prognostic significance with respect to melanoma for the first time, while HCP5 has been reported to inhibit the development of cutaneous melanoma." (PMID 33868993, 2021). "Among these, CLEC7A, CLEC10A, and HAPLN3 have not yet been reported to be correlated with melanoma before." (PMID 33868993, 2021).
COVID-19 (10 papers, 2021 to 2025). A disease caused by infection with severe acute respiratory syndrome coronavirus 2. "CLEC10A interacts with the Spike protein of SARS-CoV-2, and this interaction leads to a marked pro-inflammatory response in myeloid cells, which directly correlates with the severity of COVID-19." (PMID 38104081, 2023). "Furthermore, plasma IL-8, IL-6, TNFRSF11B, and CSF EZR levels were allied to severe COVID-19 using the ordinal backward and best linear model, whereas plasma 4E-BP1 and CSF levels of PD-L1, BMP-4, CLEC10A and ROBO2 withstanded using one model only." (PMID 36351919, 2022).
glioblastoma (9 papers, 2023 to 2025). The most malignant astrocytic tumor (WHO grade IV). "An alternate view of CLEC10A function emerged from dose–response studies of treatment of murine models of ovarian cancer and glioblastoma with peptides." (PMID 36840010, 2023).
ovarian carcinoma (8 papers, 2014 to 2023). A malignant neoplasm originating from the surface ovarian epithelium. "CLEC10A was reported to play an important role in immune cell maturation and CLEC10A expression is known to correlate with improved survival in breast and ovarian cancers." (PMID 33868993, 2021). "In this study, we asked whether a peptide that binds in the GalNAc-binding site of CLEC10A would serve as an effective tool to activate an immune response against ovarian cancer." (PMID 29665849, 2018). "GalNT6 is up-regulated in breast and ovarian cancer initiating the O-glycosylation of MUC1, which we identified as a major ligand of CLEC10A." (PMID 31455323, 2019). "As an immunotherapy target, CLEC10A has proven to be an effective tool for activating the immune response in ovarian cancer although its function in colon cancer has not been explored." (PMID 33401247, 2020).
viral infection (4 papers, 2019 to 2024). "Reductions in XCR1+ cDC1 and CLEC10A+ cDC2 may have functional implications for susceptibility to viral infections and tumor surveillance in CLL." (PMID 39399662, 2024).
colon cancer (3 papers, 2020 to 2023). "IRG signature of AXIN2, CCL22, CLEC10A, CRIP2, RUNX3, and TRPM5 is a reliable prognostic predictor for colon cancer patients." (PMID 33401247, 2020).
Obesity (3 papers, 2021 to 2024). Accumulation of substantial excess body fat. "Eighteen of those genes have reported associations with T2D and obesity in humans; of these genes there was most marked evidence for CLEC10A, MAPK8IP1, NEGR1, NQ01 and INHBE genes." (PMID 34391409, 2021).
allergic dermatitis (2 papers, 2020). "Allergic hypersensitivity and immunopathology can also be mediated by CTLs: in horses, Dectin-1, Dectin-2, and macrophage lectin 2 (MGL/Clec10a) may contribute to severe allergic dermatitis following insect bites." (PMID 32698416, 2020).
breast tumor (2 papers, 2014 to 2026). "Together, these findings support a relationship between tumor glycosylation and CLEC10A/CD301b-associated myeloid regulation, highlighting this axis as a potential target for reprogramming the breast tumor immune microenvironment." (PMID 42147159, 2026). "Here, we identify the C-type lectin receptor CD301b (encoded by Mgl2) as a regulator of immune activity within the breast tumor microenvironment (TME) and identify a cross-species myeloid regulatory program associated with its human ortholog CLEC10A." (PMID 42147159, 2026).
Cirrhosis (2 papers, 2023 to 2024). A chronic disorder of the liver in which liver tissue becomes scarred and is partially replaced by regenerative nodules and fibrotic tissue resulting in loss of liver function. "Finally, our scRNAseq analysis shows the presence of DAMs in the liver of NAFLD patients, which share the same phenotype, including expression of TREM2, CD9, GPNMB, MHCII (HLA-DRB1), C1QA, and CLEC10A, as those found in the livers of patients with NASH and cirrhosis." (PMID 38280848, 2024).
lung adenocarcinoma (2 papers, 2021 to 2023). A carcinoma that arises from the lung and is characterized by the presence of malignant glandular epithelial cells. "CLEC10A also has diagnostic, prognostic, and immune-implicated significance in lung adenocarcinoma." (PMID 37507593, 2023). "However, there is no functional research of CLEC10A in prognostic risk, immunotherapy or any other treatment of lung adenocarcinoma (LUAD)." (PMID 33655701, 2021).
metastatic disease (2 papers, 2021 to 2025). "Given that 40% of the MPNST samples were metastatic tumors collected from the lung, the identification of CLEC10A + and S100B + lung specific DC was expected." (PMID 40585258, 2025).
osteosarcoma (2 papers, 2024 to 2025). A usually aggressive malignant bone-forming mesenchymal neoplasm, predominantly affecting adolescents and young adults. "It has recently been reported that the ligands recognized by C-type lectin CD301 (CLEC10A/MGL), which bind with the Tn and sialyl-Tn antigens, were identified as moderately to strongly expressed in approximately 26% of osteosarcoma tissue samples." (PMID 40864783, 2025). "To investigate potential glycan-targeting structures for immunotherapy, we stained primary osteosarcomas with recombinant C-type lectin CD301 (MGL, CLEC10A) and observed moderate to strong staining on 26% of the tumors." (PMID 38791381, 2024).
Salmonella Infections (2 papers, 2011 to 2021). Infections with bacteria of the genus SALMONELLA. "Within the current critical region, one gene, Mgl1/Clec10a, and one QTL controlling susceptibility to Salmonella infection, Ity2, were proposed as candidates for controlling host response at Ltxs2." (PMID 22241984, 2011).
Stroke (2 papers, 2021 to 2025). Sudden impairment of blood flow to a part of the brain due to occlusion or rupture of an artery to the brain. "Therefore, we isolated CD11b-positive cells from the infarct area at day 3 post-stroke, and then analyzed the mRNA level of Clec10a in these cells." (PMID 34122007, 2021).
uveitis (2 papers, 2024 to 2025). An inflammatory process affecting a part of or the entire uvea. "Moreover, Th17‐related monocytes that highly express lncRNA XIST, CLEC10A, CX3CR1, and THBS1, which are considered critical alarmins that induce inflammation, may be the most feasible hub genes for AS‐associated uveitis and have been found to participate in Th17 cell differentiation." (PMID 39473904, 2024).
asthma (1 paper, 2014). "This study provides evidence for an augmented expression of CCL13, CCL17, and CLEC10A in AMΦ from patients with mild asthma during episodes of acute allergic airway inflammation." (PMID 24612750, 2014).
dermatitis (1 paper, 2022). An inflammatory process affecting the skin. "In an animal model, it was suggested that the C-type lectin receptor Clec10a in mice and the similar Asgr1 protein in humans, regulate the inflammation associated with mite-induced dermatitis." (PMID 35334542, 2022).
eosinophilia (1 paper, 2014). "The mRNA expression of CCL17 and CLEC10A correlated significantly with the degree of eosinophilia (each P < .01)." (PMID 24612750, 2014).
helminth infections (1 paper, 2016). "We found both Mrc1 and Clec10a to be consistently up-regulated by helminth infections." (PMID 27058578, 2016).
tumor (70 papers, 2008 to 2026). "Among different cancer types (ER+, HER2+ and TNBC) and other tumor-associated cells, we almost exclusively observed CLEC10A expression in the myeloid cell cluster, preferentially in cDC2 and IL1B+ monocytes of which more than 40% of cells expressed CD301." (PMID 38206856, 2024). "CLEC10A recognizes and acts on tumour‐associated Tn antigens and effectively presents the antigens to CD4 T cells." (PMID 33655701, 2021). "In this research, we revealed that the raising expression level of CLEC10A was obviously linked to the increasing infiltration level of various TIICs in tumour tissues." (PMID 33655701, 2021). "CLEC10A was also found to bind tumor-associated sialylated-GalNAc antigens, Neu5Acα2,6-Tn, and NeuGcα2,6-Tn with similar affinities." (PMID 32650396, 2020). "Alternatively-activated, tumor-associated macrophages, in particular the classical immunosuppressive M2a type, express CLEC10A." (PMID 29665849, 2018). "CLEC10A+ TAMs expressed high levels of the CLEC10A gene, which could recognize and act on tumor-associated antigens and effectively present the antigens to T cells." (PMID 40230843, 2025). "Moreover, CLEC10A is expressed at higher levels by tumor-associated macrophages and microglial cells in the brain." (PMID 32650396, 2020). "GlycoChat identified CLEC10A and SIGLEC3 as lectin receptors expressed on tumor-associated macrophages that interact with cancer cell surface glycans." (PMID 41532420, 2026). "In the mDCs group, CD1C+ mDC (CD1C, FCER1A, and CLEC10A) were reduced in the tumor compartment compared to the adjacent kidney." (PMID 36180422, 2022). "Currently, several researchers have focused on the ability of CLEC10A to promote the anti-tumor activity of immune cells, and it has been reported that CLEC10A plays an indispensable role in increasing antigen-specific CD8+ T cell activation." (PMID 36497444, 2022). "And the expression level of CLEC10A has a significant effect on the clinical parameters including primary tumour status, lymph node metastasis status and tumour pathological stages." (PMID 33655701, 2021). "These inconsistent conclusions illustrate accurately the complex mechanism of CLEC10A role in tumour tissue." (PMID 33655701, 2021). "Decreased CLEC10A expression leads to worsening of clinical features (primary tumour scope, distant metastasis, pathological stage of tumour and prognosis)." (PMID 33655701, 2021). "In this study, we conducted a comprehensive analysis of CLEC10A expression in the risk of LUAD progress based on more than 1200 patients, and then correlated CLEC10A different expression level and the alteration of tumour immune microenvironment." (PMID 33655701, 2021). "The role of CLEC10A in improving the anti‐tumour activity of immune cells has clearly received people's attention and proposed it as a target for cancer immunotherapy." (PMID 33655701, 2021). "We recommend strongly that researchers in the field of tumour immunology conduct further research on CLEC10A in LUAD to gradually elaborate the biological function of CLEC10A in the immune microenvironment and prognosis of LUAD patients." (PMID 33655701, 2021). "The CLEC10A’ s function in improving the anti‐tumour activity of immune cells has clearly received people's attention and proposed it as a target for cancer immunotherapy." (PMID 33655701, 2021). "These clearly show that the increasing expression of CLEC10A could ameliorate the immune microenvironment of tumours in LUAD patients by raising the infiltration level of immune cells, thereby improving patients’ prognosis." (PMID 33655701, 2021). "Therefore, it was confirmed that CLEC10A participating widely in modulating various immune molecules in LUAD to affect immune infiltration in the tumour microenvironment." (PMID 33655701, 2021). "Moreover, CLEC10A expression was significantly correlated with a variety of the tumour‐infiltrating immune cells (TIICs)." (PMID 33655701, 2021).
tumor (continued). "Bulk RNA-seq analysis of CD1c+CD14+ cells sorted from tumor-invaded lymph nodes indicated that they displayed a similar expression profile as blood DC3s (high expression of cDC2 markers such as CLEC10A and FCER1A combined with low expression of monocyte-associated markers such as C5AR1 and SOD2)." (PMID 32610077, 2020). "The exposed Tn antigen is the ligand of Ca2+dependent C-type lectin receptor MGL (macrophage galactose type lectin/CD301/CLEC10A), MGL specifically recognizes tumor derived mucin MUC1 by binding to Tn antigen." (PMID 38699634, 2024). "In order to study the expression patterns of genes in tumors and normal cell lines, PCR was used to detect the mRNA expression of genes, and the results showed that the expression of SPARCL1, HAND1, CLEC10A, PTGS1 genes in tumor group was significantly lower than that in the normal group." (PMID 35281077, 2022). "CLEC10A and CRIP2 were negative in both normal and tumor tissues." (PMID 33401247, 2020).